MEG3 (maternally expressed 3)
Diseases named in the same sentence as MEG3 in open-access papers (continued):
Sharing a sentence is not in itself a finding about the gene and the disease.
cancer (continued). "Much evidence has indicated that MEG3 polymorphisms are linked with cancer susceptibility." (PMID 39049088, 2024). "Loss of MEG3 activity in these different cancer types is attributed to aberrant DNA methylation." (PMID 37525401, 2023). "Consequently, MEG3 is implicated in the inhibition of cancer cell growth and the induction of apoptosis." (PMID 38066437, 2023). "In addition, certain polymorphisms (rs3087918 T>G, rs11160608 A>C, rs4081134 G>A, rs7158663 A>G) within the MEG3 gene are implicated in cancer susceptibility." (PMID 34956908, 2021). "LncRNAs HOTAIR, MALAT1, MEG3, and H19 are associated with a large number of cancer types." (PMID 34680193, 2021). "The integration of the differentially expressed ncRNAs, with an exhaustive computational analysis of their experimentally supported targets, led us to dissect complex networks integrated by the cancer-related lncRNAs Malat1, Neat1, H19, Meg3, and their associated miRNA-target pairs." (PMID 34222014, 2021). "MEG3 polymorphisms have been linked to cancer risk and therapeutic response in cancer patients." (PMID 34421993, 2021). "Based on these results, MEG3 polymorphisms could be used as a potential predictive biomarker for platinum-based adjuvant chemotherapy responses in relevant cancer patients." (PMID 34199840, 2021). "MEG3 is expressed in many normal tissues and its loss has been reported in many cancer types." (PMID 32154165, 2020). "It is also reported that SNPs in MEG3 gene have an influence on cancer risk." (PMID 32669097, 2020). "Through the integration of annotation information on mRNAs, we found that MEG3 and its synergistic miRNAs were mainly associated with cancer-related processes such as immune system development, cell development, tissue development, cell differentiation, protein metabolism, and other processes." (PMID 33101392, 2020). "In addition, we found DAMEs corresponding to known regions exhibiting loss of imprinting in cancer, including those in the genes MEG3, H19, and GNAS." (PMID 32487212, 2020). "Screening for structure-disrupting mutations in the MEG3 gene, particularly in the two key functional motifs H11 and H27, may also serve as a useful biomarker for identifying patients with increased cancer susceptibility." (PMID 31444106, 2019). "LncRNA Meg3 located at chromosome 14q32 could encode a 1.5kb length transcript related to various human cancers." (PMID 31761787, 2019). "However, single nucleotide polymorphisms (SNPs) in MEG3 were reported to affect cell phenotypes and cause the risk of developing cancer and the chemotherapy toxicity in other cancers." (PMID 31488093, 2019). "The associations between MEG3 polymorphisms and cancer risks have been also investigated." (PMID 29615542, 2018). "Accumulating evidence has suggested that genetic variants in the MEG3 gene predispose to cancer." (PMID 29615542, 2018). "In this meta-analysis, we evaluate the association between expression levels of MEG3 and cancer." (PMID 28157702, 2017). "Different mechanisms may contribute to the decrease or loss of MEG3 expression in cancers, including hypermethylation of the regulatory regions and deletions of the gene, as well as post translational degradation via miRNAs." (PMID 29069869, 2017). "However, no meta-analysis was been conducted assess the association between MEG3 and the survival of patients with cancers." (PMID 28157702, 2017). "Dysregulation of MEG3 has been associated with several types of cancer." (PMID 28407691, 2017). "Down regulation of lncRNA MEG3 had been reported closely associated with several cancers." (PMID 27634882, 2016). "Similarly, loss of MEG3 expression has also been found in many cancer cell lines including those derived from brain, bladder, bone marrow, breast, cervix, colon, liver, lung, meninges and prostate." (PMID 24098911, 2013).
cancer (continued). "Altogether, it seems that the MEG3 is a lncRNA with a diverse range of functionalities and more investigations are needed to disclose its unknown functions and underlying mechanisms in cancers like leukemia." (PMID 40486167, 2025). "All biochemical processes in which MEG3 is involved make it an excellent marker for BC prognosis: circulating MEG3 status in tumors may be useful also for selecting patients who are most likely to benefit from adjuvant therapy, which is used to reduce the risk of cancer recurrence." (PMID 29165379, 2017). "CASC2a, downregulated in the cancer, inhibits growth through epigenetic gene inactivation, contrasting with MEG3’s approach." (PMID 40242248, 2025). "This synergistic effect highlights MEG3’s potential to enhance chemosensitivity and improve outcomes in advanced or treatment-resistant cancers." (PMID 40242248, 2025). "Despite thorough research on the function of the lncRNA MEG3 in many forms of cancer, there are still few studies examining its role in the relationship between AD and T2D." (PMID 40869265, 2025). "MEG3’s potential for improving diagnostics and therapeutic strategies offers exciting opportunities for advancing treatment options in these cancers." (PMID 40242248, 2025). "Marker genes that were highly expressed in this group of cells include the cancer-associated imprinted genes XIST, NEAT1, and MEG3." (PMID 40585258, 2025). "In the context of HBV infection, the weakened anti-cancer immune effect is due to decreased levels of IFN-γ and TNF-α as a consequence of the loss of MEG3." (PMID 40625740, 2025). "The induction of apoptosis and inhibition of cancer cell proliferation is achieved through the reintroduction of maternally expressed gene 3 (MEG3) long non-coding RNA (lncRNA) in cancer cells." (PMID 40428088, 2025). "MEG3, as a critical tumor suppressor gene, has the paramount potential to orchestrate many cancer hallmarks." (PMID 40242248, 2025). "Continued research and development efforts are necessary to overcome these challenges, ultimately enhancing the therapeutic benefits of targeting MEG3 in cancer therapy." (PMID 40242248, 2025). "MEG3 expression has been found to correlate with the prognosis of cancer patients and the pathological grade of malignancy." (PMID 40548301, 2025). "Contribution of MEG3 in induction of drug-resistance in other cancers, such as lung cancer (cisplatin resistance), and colorectal cancer (oxaliplatin resistance), also was shown in other studies." (PMID 40486167, 2025). "The downregulation of MEG3 has been reported in several works presented in this review and therefore, plays a critical role in normal liver function if lost in cancer." (PMID 40625740, 2025). "In another study, it is found that the long non-coding RNA Meg3 enhances miR-3163-mediated suppression of Skp2 protein translation, inhibiting cancer cell growth in NSCLC." (PMID 40396180, 2025). "The Maternally Expressed Gene 3 (MEG3) is a long non-coding RNA expressed in a tissue-specific manner and plays a role in the development of several diseases, particularly in cancer." (PMID 40149464, 2025). "Among them, maternally expressed gene 3 (MEG3) emerged as one of the frequently deregulated lncRNAs that played a vital role in cancer development." (PMID 40548301, 2025). "Several researchers have reported that the down-regulation of MEG3 influences the proliferation and progression of cancer cells." (PMID 39108882, 2024). "Previous studies have confirmed that MEG3 plays an antitumor role in various other cancers, including gynecological malignancies." (PMID 38281945, 2024).
cancer (continued). "An increasing number of studies have shown that lncRNA MEG3 is hypermethylated and downregulated in various cancer tissues and cancer cell lines, playing the role of a tumor suppressor gene, and that it is a good biomarker for cancer diagnosis and prognosis." (PMID 39062818, 2024). "Reduced levels of MEG3 have been detected in cervical cancer, influencing cancer cell growth via miR-21." (PMID 39553554, 2024). "We investigated the expression level of MEG3 in pan-cancer through bioinformatics analysis, especially in gynecological tumors." (PMID 38281945, 2024). "For instance, studies have shown that the lncRNA MEG3 inhibits cancer cell migration and invasion by modulating the expression of genes related to metastasis." (PMID 39257589, 2024). "The downregulation of MEG3 is correlated with enhanced cancer cell proliferation and potentially poor prognosis." (PMID 39553554, 2024). "In contrast, MEG3 is downregulated in cancer and has many physiologically expressed isoforms, while we are studying the variant that has PQS." (PMID 37628839, 2023). "As a take home message from this study, the role of MEG3 lncRNA cancer cells requires further attention to be fully understood." (PMID 37525401, 2023). "MEG3, as a cancer suppressor, is regulated by methylation, resulting in decreased expression, especially in drug-resistant cell lines." (PMID 37901333, 2023). "Here, we propose that the MEG3 lncRNA plays a complicated role that changes for different cancer types." (PMID 37525401, 2023). "Maternally expressed gene 3 (MEG3) is a LncRNA located on chromosome 14q32.3 and is downregulated in human cancers." (PMID 36770654, 2023). "The lncRNA MEG3 was found to be significantly reduced and correlated with cancer stage, metastasis, and other factors." (PMID 37007117, 2023). "MEG3 is involved in a variety of cancers through the inhibition of cell growth/proliferation, migration, and invasion, and the promotion of cancer cell apoptosis." (PMID 36851033, 2023). "Among these DElncRNAs, some were proven to participate in cancer development, invasions, progressions, and drug resistance, such as MEG3, MIAT, and MIR200CHG." (PMID 37511974, 2023). "By inhibiting DNA methylase, the DLK1-MEG3 imprinted domain, which contains the tumor suppressor factor MEG3 lncRNA, promotes cancer growth." (PMID 37245177, 2023). "In this respect, Meg3′s repressive trans effects in cancer cells and neurons seem mechanistically similar to its effect in cis at the Dlk1-Dio3 domain, where it enhances the local levels of H3K27me3 and represses gene expression as well." (PMID 37686455, 2023). "In different types of cancer, including pituitary adenomas, ovarian cancer, and pancreatic neuroendocrine tumours, among others, there is reduced expression of MEG3." (PMID 37686455, 2023). "In this review, we summarize the general functions of lncRNA maternally expressed gene 3 (MEG3) in cancers and its involvement in metal carcinogenesis." (PMID 36851033, 2023). "They suggested that MEG3 suppresses migratory features of gastric cancer cells by modulating EMT in these cancer cells." (PMID 36770654, 2023). "In humans, the Rian ortholog, MEG8 (along with MEG3), has been shown to be upregulated in many cancers and is thought to regulate many different pathways by acting as a molecular sponge for various miRNAs." (PMID 38155837, 2023). "With the knockdown of the upstream inhibitory target DNMT1, the highly expressed MEG3 shows high potential for cancer inhibition, including inhibiting cancer cell proliferation and promoting apoptosis, and inhibiting EMT through Notch1 signaling pathway." (PMID 37901333, 2023).
cancer (continued). "The major pathways of MEG3 in the regulation of cancer cell proliferation, migration, and invasion are summarized in the following subsections." (PMID 36851033, 2023). "Individual enrichment analysis of the miRNAs related to MEG3 (ENST00000398461) showed that 26.4% of the enriched pathways are directly related to cancer." (PMID 38027526, 2023). "Maternally expressed gene 3 (MEG3) lncRNA is characterized as a tumor suppressor gene and its downregulation has been shown in many cancers, including GC." (PMID 35186192, 2022). "The expression level of the selected gene was also compared between CIN and cancer samples, revealing significant differences for the MEG3 gene." (PMID 35682732, 2022). "The maternally-expressed MEG3 gene, along with RTL1, MEG8/8, and DIO3, are regulated by the DLK/MEG3 ICR which is also a well-studied cancer-associated locus." (PMID 36142363, 2022). "Recently, many studies have demonstrated that MEG3 exerts anti-cancer effects through the lncRNA-miRNA-mRNA axis." (PMID 36544907, 2022). "Although MEG3 has been reported as the anti-fibrotic and anti-cancer lncRNA, some studies can support our findings." (PMID 35890132, 2022). "An lncRNA named maternally conveyed gene 3 (MEG3) is an lncRNA that functions as a tumor suppressor in several types of cancers." (PMID 35422450, 2022). "Studies of newborns living in disadvantaged neighborhoods found higher global methylation; higher cord blood leukocyte DNAm of a cancer-relevant gene, MEG3; and differential DNAm at the SLC6A4 gene." (PMID 35380065, 2022). "The loss of long non-coding RNA (lncRNA) maternally expressed 3 (MEG3) expression is observed in various types of disorders, such as cancers and fibrotic disease." (PMID 35890132, 2022). "MEG3 is expressed in primary cells, while in cancer cell lines it is usually expressed at low levels." (PMID 35741072, 2022). "MEG3 exerted an anti‐cancer effect via stimulatory effects on EZH2 ubiquitination leading to its degradation." (PMID 35257481, 2022). "This study analyzed the MEG3 expression in pan-cancers by bioinformatics analysis, and the results demonstrated that MEG3 was decreased in most of cancers." (PMID 36033389, 2022). "For instance, MEG3 can inhibit the invasion as well as proliferation of cancer cells through enhancing EZH2 ubiquitination in gallbladder cancer cells." (PMID 35422450, 2022). "In this study, we determined levels of several miRNAs vital for cancer cell biology, including miR-21, miR-124, miR-223 and miR-320, and long-non-coding RNA MEG3." (PMID 36139691, 2022). "LncRNA maternally expressed gene 3 (MEG3) has been reported to be lost or reduced in many human tumors, and MEG3 changes in various cancers suggest that it has the possibility to diagnose and evaluate the prognosis of cancer." (PMID 35794862, 2022). "MEG3 can facilitate chemotherapeutic drug sensitivity and radiosensitivity by altering key signaling pathways, making it a novel therapeutic strategy for cancer treatment." (PMID 36551518, 2022). "Together, these findings suggest that MEG3 plays a significant role in enhancing chemotherapeutic drug sensitivity and radiosensitivity in a variety of human cancers, making it a potential therapeutic target for cancer treatment." (PMID 36551518, 2022). "In the case of normal vs. cancer samples, significant differences were observed for the expression of MEG3, TIMP3 and MALAT1." (PMID 35682732, 2022). "This review discusses the molecular mechanisms of MEG3 in different tumors and future challenges for the diagnosis and treatment of cancers through MEG3." (PMID 36544907, 2022). "MEG3 governed several cancer-relevant signal transduction pathways, such as TGF-β, PI3K/Akt, Notch, mTOR, and Wnt/β-catenin signaling cascades." (PMID 35656022, 2022).
cancer (continued). "In the case of CIN versus cancer samples, only MEG3 gene showed a statistically significant difference." (PMID 35682732, 2022). "Results showed that MEG3 expression was lower in most of the human cancer tissues than in the normal tissues." (PMID 34220951, 2021). "The advancements of the current study were that we targeted MEG3 at single cell levels of purified cancer cells, and these cells were at the natural stages of in vivo tumors." (PMID 34055623, 2021). "Three thyroid-specific genes (TG, TPO, and NIS), six cancer-associated lncRNAs (MALAT1, NEAT1, HOTAIR, H19, PVT1, MEG3), and two housekeeping genes (GAPDH and P0) were analyzed using Droplet Digital PCR (ddPCR)." (PMID 33030666, 2021). "Nevertheless, accumulating studies have reported the pro‐apoptotic and pro‐autophagic effects of MEG3 on cancer cells in various human cancers." (PMID 33332708, 2021). "Clinically, Meg3 levels strongly correlated with the clinicopathological outcomes of various cancers." (PMID 34934045, 2021). "A number of studies have suggested that the expression of MEG3 is downregulated in several types of cancer cells, and DNA methylation has been proven to play a significant role in silencing MEG3 in tumors." (PMID 34069546, 2021). "MEG3 expression level in different human cancers and normal tissues were analyzed using Oncomine database." (PMID 34220951, 2021). "The lncRNAs HOTAIR, MALAT1 and MEG3 were also enriched in EVs derived from cervical-vaginal lavages and significantly upregulated in CC patients compared with cancer-free volunteers." (PMID 34552067, 2021). "LINC001133 was predominantly expressed in a less aggressive cluster in primary cancer cells, while MEG3 was primarily expressed in a metastatic cancer cell cluster, which displayed increased EMT signatures and was potentially leading cancer cell metastasis." (PMID 34055623, 2021). "We first analyzed, by ddPCR expression of several cancer-associated lncRNAs (MALAT1, NEAT1, HOTAIR, H19, PVT1, MEG3) in both FNAs and surgical specimens and selected MALAT1, HOTAIR, and PVT1 as cancer biomarkers." (PMID 33030666, 2021). "PrognoScan was used to investigate the potential prognostic impact of MEG3 expression level in patients suffering from different types of cancer." (PMID 34220951, 2021). "Although, circulatory MEG3 has shown biomarker value in other cancers, such as colorectal, gastric, breast, bladder, and pancreatic." (PMID 34322395, 2021). "Analysis pertaining to the prognostic impact showed that increased expression of MEG3 was correlated with improved survival in multiple types of human cancers." (PMID 34220951, 2021). "Meg3 exhibits its biological roles via miRNAs that have been identified based on their roles in cancer, including (for example) miR-141 in chemotherapy, miR-212 in EMT, miR-19a and miR-93 in the cell cycle, and miR-21-5p in cell apoptosis." (PMID 34934045, 2021). "Meg3 showed rare transcript in normal epithelial cell but was significantly elevated in the cancer cells of PDAC mouse models with the exception of Late KPC due to extremely low cell number in this model." (PMID 34055623, 2021). "LINC01133 positive and MEG3 positive cells were well separated in the integrated cancer cell data and showed little overlap." (PMID 34055623, 2021). "In some pathways associated with cancer, such as TGF-β, PI3K/AKT, mTOR, and WNT/β-catenin pathways, MEG3 plays a regulatory role." (PMID 34199840, 2021).